ANO1 (anoctamin 1)
Diseases named in the same sentence as ANO1 in open-access papers (continued):
Sharing a sentence is not in itself a finding about the gene and the disease.
prostate carcinoma (continued). "High expression of ANO1 in HNSCC, ESCC and prostate cancer correlates with a higher risk of distant metastasis and a shorter survival of these patients." (PMID 25823819, 2015). "The study reached a conclusion: the higher the expression of ANO1, the higher the malignancy of the prostate cancer." (PMID 24639373, 2014). "The findings provided compelling evidence for the close correlation of ANO1 overexpression in prostate cancer tissues with their proliferation and metastasis." (PMID 24639373, 2014). "ANO1 proteins were highly expressed in prostate cancer tissues and metastatic prostate cancer cell lines, LNCaP and PC-3, and produced high density of CaCC currents." (PMID 24639373, 2014). "With the human pathologic tissue specimens from patients (classified by TNM staging) and human tissue arrays by IHC with specific antibody against ANO1, the expression of ANO1 was found to be closely correlated with the malignancy of the prostate cancers." (PMID 24639373, 2014). "Additionally, some studies have shown that natural products such as resveratrol and luteolin can act as ANO1 inhibitors while also exhibiting anti-tumor activities, effectively suppressing the proliferation and migration of prostate cancer cells." (PMID 40356890, 2025). "Interestingly, cis-resveratrol demonstrated a more potent inhibition of ANO1 activity compared to trans-resveratrol, as well as a stronger effect on inhibiting cell growth and migration in PC-3 prostate cancer cells." (PMID 39942639, 2025). "Considered together, these initial observations suggest that DNA methylation plays a critical role in down-regulating ANO1 expression and that 5-Aza-CdR treatment efficiently attenuates DNA-methylation-induced ANO1 silencing in prostate cancer cells with low metastatic potential." (PMID 38773164, 2024). "Taken together, these data underscore the essential role for ANO1 in upregulating migration and invasion abilities of prostate cancer cells and support the concept that ANO1 is a necessary factor to upregulate genes encoding potential inducers of metastasis in prostate cancer cells." (PMID 38773164, 2024). "Interestingly, hemin, a novel ANO1 inhibitor, showed anticancer effects dependent on ANO1 expression in PC-3 prostate cancer cells." (PMID 38892219, 2024). "This study represents an extensive analysis of DNA methylation at the ANO1 gene locus and provides important insights into how ANO1 expression is epigenetically regulated in prostate cancer cells, extending our view on DNA methylation as a key determinant of prostate cancer development." (PMID 38773164, 2024). "Specifically, ANO1 has been reported as a new drug target for prostate cancer." (PMID 38892219, 2024). "Interestingly, recent studies revealed that ANO1 is highly expressed in prostate cancer, and the inhibition of ANO1 demonstrated anticancer effects." (PMID 38892219, 2024). "Therefore, in the present study, we investigated the ANO1-dependent anticancer effects of hemin, a novel ANO1 inhibitor, in prostate cancer cells." (PMID 38892219, 2024). "Considering that DNA methylation is a vital epigenetic mechanism that cells use for gene silencing, we hypothesized that DNA methylation could potentially attenuate the expression and thus function of ANO1 in prostate cancer cells." (PMID 38773164, 2024). "However, luteolin, which strongly reduces ANO1 protein expression, inhibited prostate cancer cell proliferation more effectively than kaempferol, which does not." (PMID 38892219, 2024). "In addition, cis-resveratrol downregulated mRNA and protein expression levels of ANO1 more potently than trans-resveratrol in PC-3 prostate cancer cells." (PMID 36674697, 2023). "In addition, they showed how RSV also decreased the expression of ANO1 protein and mRNA in PC-3 prostate cancer cells." (PMID 38026933, 2023). "Furthermore, pharmacological inhibition and downregulation of ANO1 showed anticancer effects in metastatic prostate cancer cells." (PMID 36674697, 2023).
prostate carcinoma (continued). "Notably, cis-resveratrol exhibited a stronger inhibition of ANO1 activity than trans-resveratrol and a stronger cell growth and migration inhibitory effect in PC-3 prostate cancer cells." (PMID 36674697, 2023). "In addition, downregulation of ANO1 with the treatment of ANO1 shRNA significantly decreased tumor growth in a prostate cancer xenograft mouse model." (PMID 32899792, 2020). "Interestingly, HaCaT cells, a spontaneously immortalized human keratinocyte, and PC-3 prostate cancer cells express similar levels of ANO1 protein; however, ANO1 knockdown more strongly reduced cell proliferation of PC-3 cells compared with HaCaT cells." (PMID 32899792, 2020). "Emerging evidence suggests that ANO1 inhibitors could be a feasible approach to treat prostate cancer, oral cancer, and various other carcinomas that express high levels of ANO1." (PMID 32899792, 2020). "To test this hypothesis, we utilized genetic and pharmacological approaches to investigate the effect of ANO1 expression on TNF-α signaling in prostate cancer cells." (PMID 29899325, 2018). "Furthermore, higher expression of ANO1 was observed in cancer tissue compared with normal counterpart tissue in gastric carcinomas, hepatocellular carcinoma, and prostatic carcinomas." (PMID 29416639, 2018). "ANO1 expression is inversely correlated with TNF-α expression in prostate cancer cells." (PMID 29899325, 2018). "For instance, molecular and electrophysiological studies showed strong and functional expression of ANO1 in human metastatic prostate cancer PC-3 cells, and downregulation of ANO1 expression by shRNA induced significant reduction of cell proliferation, metastasis and invasion." (PMID 28362855, 2017). "Indeed, it has been reported that blocking chloride channel inhibits migration of nasopharyngeal carcinoma cells, and that inhibition of ANO1 suppressed the migration of prostate carcinoma cells in vitro." (PMID 24316695, 2014). "Furthermore, immunohistochemical analysis indicated that ANO1 was upregulated in human prostate cancer specimens, and this heightened expression corresponded with advanced clinical staging and more aggressive disease traits, pointing to its potential as a prognostic biomarker for prostate cancer." (PMID 40707942, 2025). "Therefore, we hypothesize that hemin may elicit potent anticancer effects in prostate cancer cells through the dual mechanisms of ANO1 channel blockade and ANO1 downregulation." (PMID 38892219, 2024). "Although the physiological functions of ANO1 are diverse and include secretion of chloride ions and the development of cancer, the inhibition of the function of ANO1 channel and reduction of its protein expression has therapeutic effects in head and neck cancers, and in prostate cancers." (PMID 37274097, 2023). "Therefore, to develop a lead compound for lung cancer treatment, we used an FDA-approved drug library with excellent properties and safety measures in places and discovered a hit compound, DES, that inhibits ANO1 and which is currently used as a prostate cancer treatment agent." (PMID 34281152, 2021). "Therefore, suppressing ANO1 or enhancing TNF-α signaling may serve as a therapeutic strategy for potential treatment of human prostate cancer." (PMID 29899325, 2018). "In summary, ANO1 is overexpressed in highly metastatic PC3 cells, but shows minimal expression in low metastatic LNCap and DU145 prostate cancer cells, indicating its possible role in regulating metastatic potential in prostate cancer." (PMID 38773164, 2024). "We found that the gene expression of KCa3.1 and ANO1 was epigenetically regulated by HDAC3 in breast and prostate cancers." (PMID 39273558, 2024). "To stimulate Cl- flow through ANO1, we treated LNCap, DU145, PC3 prostate cancer cells with N-aroylaminothiazole (Eact) which is a specific agonist for ANO1." (PMID 38773164, 2024).
prostate carcinoma (continued). "Using these ANO1-depleted cells, we examined whether the reactivation of ANO1 in response to 5-Aza-CdR treatment could influence the migratory and invasive abilities of prostate cancer cells, which are considered as critical determinants for metastatic cell dissemination." (PMID 38773164, 2024). "Here, we show that ANO1 is minimally expressed in LNCap and DU145 prostate cancer cell lines with low metastatic potential but overexpressed in high metastatic PC3 prostate cancer cell line." (PMID 38773164, 2024). "Collectively all these results are supportive of the view that DNA demethylation is a critical mechanism for inducing ANO1 expression and functional activation on the membrane of LNCap and DU145 prostate cancer cells." (PMID 38773164, 2024). "Therefore, ANO1 may be a promising therapeutic target for prostate cancer." (PMID 38892219, 2024). "Furthermore, strong expression of ANO1 in PC-3 cells and its decrease after shRNA treatment were observed, and downregulation of ANO1 expression by intratumoral injection of ANO1 shRNA in a xenograft mouse model of prostate cancer using PC-3 cells significantly inhibited tumor growth." (PMID 38892219, 2024). "One of the key observations made in our analysis was much lower expression of ANO1, ANO8 and ANO10 in LNCap low-metastatic and DU145 moderately-metastatic cells when compared to PC3 highly-metastatic prostate cancer cells." (PMID 38773164, 2024). "The high expression of ANO1 in HNSCC, ESCC, and prostate cancer reportedly increases metastasis and decreases the survival rate of patients." (PMID 34281152, 2021). "To investigate the biological function of ANO1, we compared the protein and mRNA levels of ANO1 in normal prostate epithelial cells (RWPE-1) and prostate cancer cell lines (DU145, LNCaP, 22RV1, VCaP, and PC-3)." (PMID 29899325, 2018). "Here, we show that silencing or inhibition of endogenous ANO1 inhibits cell growth, induces apoptosis and upregulates TNF-α expression in prostate cancer PC-3 cells." (PMID 29899325, 2018). "Suppression of ANO1 upregulates TNF-α expression and activates TNF-α signaling, thus promoting apoptosis in prostate carcinoma." (PMID 29899325, 2018). "ANO1 knockdown significantly increased protease expression and activation of caspase-8, caspase-3, caspase-7, and PARP (poly ADP-ribose polymerase) in prostate cancer PC-3 cells." (PMID 29899325, 2018). "ANO1 is amplified and highly expressed in several types of human carcinomas including head-and-neck squamous cell carcinoma (HNSCC), GIST, breast and prostate cancer." (PMID 27219012, 2016). "For instance, pharmacological inhibition of ANO1 reduces cell viability in HNSCC, ESCC, breast cancer and prostate cancer cells." (PMID 27219012, 2016). "ANO1, a recently identified CaCC, is strongly overexpressed in various tumor types including HNSCC, GIST, breast and prostate cancer." (PMID 26196390, 2015). "Interestingly, however, high levels of ANO1 expression were detected only in some prostate cancer cell lines such as PC3, and analysis of other prostate cancer cell lines including LNCaP and DU145 cells exhibited low levels of ANO1 expression." (PMID 38773164, 2024). "Nevertheless, the exact mechanisms underlying the differential expression of ANO1 in LNCaP, DU145, and PC3 prostate cancer cells have not been well elucidated." (PMID 38773164, 2024). "Interestingly, our initial characterization demonstrated that ANO1 is expressed at significantly lower levels in low metastatic LNCap and DU145 prostate cancer cells than in high metastatic PC3 prostate cancer cells." (PMID 38773164, 2024). "Vitekwangin B was tested to determine whether it inhibited the growth of prostate cancer and NSCLC cells by decreasing ANO1 protein levels." (PMID 38659592, 2024). "Despite the growing interest in its function as a proto-oncogene, not much is known about epigenetic pathways that control of ANO1 expression in prostate cancer cells." (PMID 38773164, 2024).
prostate carcinoma (continued). "To test this hypothesis, we utilized genetic and pharmacological approaches to investigate the ANO1 expression and TNF-α signaling in prostate cancer cells." (PMID 29899325, 2018). "Recent evidence suggests that pharmacological inhibition of ANO1 may have beneficial effects on HNSCC, esophageal squamous cell carcinoma (ESCC), gastrointestinal stromal tumours (GIST), breast and prostate cancer." (PMID 27219012, 2016). "Most evidence indicates that pharmacological inhibition of ANO1 channel activity may have the potential to provide therapeutic benefits to HNSCC, ESCC, GIST, breast and prostate cancer patients." (PMID 26196390, 2015). "Several studies have indicated that ANO1 may be used as a therapeutic target of tumors because down regulation of ANO1 showed potential therapeutic benefits on HNSCC, ESCC, GIST, breast and prostate cancer." (PMID 26196390, 2015). "However it is not clear whether the observed effects of ANO1 truly reflect its physiological activities during the spread of prostate cancer to other tissues." (PMID 38773164, 2024). "Also, considering that DNA methylation mainly affects gene expression at the level of transcription, it was reasonable to speculate that transcription is the primary process through which the expression of ANO1, ANO8, and ANO10 is regulated in LNCaP, DU145, and PC3 prostate cancers." (PMID 38773164, 2024). "Electrophysiological studies indicated that luteolin potently inhibited ANO1 chloride channel activity in a dose-dependent manner with an IC50 value of 9.8 μM and luteolin did not alter intracellular calcium signaling in PC-3 prostate cancer cells." (PMID 28362855, 2017).
asthma (38 papers, 2008 to 2025). "CaCCs encoded by ANO1 have been implicated in many diseases such as systemic and pulmonary hypertension, asthma, defective epithelial ion transport in the lungs and gut, and many forms of cancer to name a few." (PMID 34488544, 2021). "Elevated ANO1 expression has been implicated in excessive mucus secretion and abnormal smooth muscle contraction, contributing to the pathophysiology of conditions such as asthma, hypertension, and diarrhea." (PMID 40356890, 2025). "In chronic lung diseases such as asthma and CF which have high susceptibly to environmental pollutants/allergens expression of ANO1 in airway epithelial cells is upregulated in the presence of mucus expression inducing interleukins- IL-4, IL-8 and IL-135,11,12." (PMID 38168913, 2024). "Because of this, ANO1 may play a role in the pathophysiological mechanisms underlying hypertension and asthma, respectively." (PMID 36836529, 2023). "Emerging evidence suggested that pharmacological inhibition of ANO1 may be beneficial in treatment of diseases associated with ANO1 such as asthma, hypertension, diarrhea, pain and cancer." (PMID 27219012, 2016). "The identification of ANO1 as the key gene responsible for CaCC function has recently advanced this field, but its biomolecular and cellular mechanisms in asthma remain incompletely defined." (PMID 40356890, 2025). "Subsequent studies showed that ANO1 is responsible for ICl(Ca) in airway myocytes and is involved in smooth muscle contraction to agonists and airway hypercontractility in asthma." (PMID 34488544, 2021). "In asthma increased ANO1 is shown to effectively modulate MUC5AC expression and mucus production." (PMID 38168913, 2024). "Taken together these studies suggest that inhibition of ANO1 could be useful in treating lung diseases such as CF and asthma." (PMID 38233410, 2024). "In addition, ANO1 has emerged as a new drug target for the treatment of cancer, pain, diarrhea, hypertension, and asthma." (PMID 30336555, 2018). "Our results suggest that Ani9 may be a useful pharmacological tool for studying ANO1 and a potential development candidate for drug therapy of cancer, hypertension, pain, diarrhea and asthma." (PMID 27219012, 2016). "The inhibition of ANO1 expression, either through ANO1 knockout or the use of small molecule inhibitors such as niclosamide, significantly reduces epithelial mucus secretion, suggesting that ANO1 inhibition could be a beneficial strategy for asthma treatment." (PMID 40356890, 2025). "Therefore, ANO1 inhibitors may be useful for the treatment of cancer, diarrhea, pain, hypertension and asthma." (PMID 27219012, 2016). "Thus, pharmacological inhibition of ANO1 may be beneficial in treatment of cancer, hypertension, pain, diarrhea and asthma." (PMID 27219012, 2016). "Recent studies have highlighted the pivotal role of ANO1 in ASM contraction and airway hyperresponsiveness in asthma, acting through the GPCRS/ANO1/VGCCS axis and enhanced cholinergic responses." (PMID 40356890, 2025). "For instance, ANO1 is strongly expressed in airway mucin-secreting cells and airway smooth muscle in ovalbumin (OVA)-induced asthma mouse model." (PMID 27219012, 2016). "Thus, the ANO1 inhibitor identified here constitutes new and readily accessible chemical tool for pharmacological dissection of ANO1 and may be a potential development candidate for drug therapy of cancer, hypertension, pain, diarrhea, asthma and other ANO1 related diseases." (PMID 27219012, 2016). "Increased ANO1 expression has been observed in both epithelial cells and ASM in allergen-sensitized mouse models, suggesting that ANO1 hyperactivity plays a pivotal role in asthma pathogenesis." (PMID 40356890, 2025). "However, many ANO1 inhibitors, including T16Ainh-A01, N-(4-methoxy-2-naphthyl)-5-nitroanthranilic acid (MONNA), and idebenone, show limited efficacy and poor selectivity for asthma treatment." (PMID 40356890, 2025).
asthma (continued). "This suggests miRNA mediated regulation of ANO1 in chronic inflammatory conditions such as asthma, COPD and CF where inhibition of ANO1 rather than activation is being preferred." (PMID 38168913, 2024).